MTOR (mechanistic target of rapamycin kinase)
Diseases named in the same sentence as MTOR in open-access papers (continued):
Sharing a sentence is not in itself a finding about the gene and the disease.
Infertility (23 papers, 2015 to 2025). "Aberrations in mTOR signaling have been linked to infertility and decreased fertilization after IVF in genetically modified mice." (PMID 37372413, 2023). "Sustained activation of mTOR in germ cells by genetic ablation of the Pten/Tsc1/Tsc2 causes untimely recruitment of primordial follicles leading to premature ovarian failure and infertility." (PMID 27036037, 2016). "Aberrant activation of mTOR signaling is implicated in this process, contributing to the suppression of autophagy, impaired decidualization, and promotion of cellular senescence, ultimately facilitating lesion progression and infertility." (PMID 41009686, 2025). "Intriguingly, mTOR pathway plays important roles in subsequent development of primordial and growing oocytes, as complete deletion of Mtor increases DNA damage, reduces oocyte quality, and causes infertility." (PMID 33448083, 2021). "However, further studies are required to determine how mTOR signaling is involved and if mTOR is dysregulated in subfertility or infertility cases associated with metabolic diseases." (PMID 30986927, 2019). "The medication rapamycin, together with other mTOR inhibitors, blocks follicular development, which can result in infertility." (PMID 41169682, 2025). "It is possible that low levels of S1P in somatic cells of Sphk1/2gc−/− mice decreased Akt/mTOR activity in oocytes, resulting in abnormal spindle assembly and then infertility." (PMID 36396932, 2022). "This provides a rationale for exploring the possible use of targeted therapies for the inhibition of the PI3K/PTEN/Akt and TSC/mTOR signaling cascades in certain ovarian dysfunctions including infertility and POF." (PMID 34575999, 2021). "On the other hand, germ cell-specific deletion of mTOR also led to infertility in mice even though these mice were viable and apparently healthy." (PMID 35002976, 2021). "Our data enables researchers to deduce drugs targeting members of the oxidant/antioxidant system and/or mTOR pathway to ameliorate putative HFD-induced infertility." (PMID 33628436, 2020). "Our studies demonstrate the ability of an mTOR activator in promoting follicle growth, leading to a potential strategy to stimulate preantral follicle growth in infertile patients." (PMID 25710488, 2015). "Together, the present findings suggested that short-term exposure to the mTOR signaling activator might be a promising therapeutic approach for infertile POI patients." (PMID 33613618, 2020). "Thus, that work suggests novel roles for mTOR in the restoration of fertility in individuals with subfertility or infertility induced by metabolic diseases." (PMID 30986927, 2019). "Indeed, since the first clinical evidence showed that men taking rapamycin were infertile, several studies have evidenced distinct roles for mTOR in spermatogenesis." (PMID 30986927, 2019). "Nevertheless, the mechanisms through which mTOR inhibitors induce infertility remain largely unknown." (PMID 30986927, 2019). "Further studies on ovarian mTOR signaling could allow the development of new infertility strategies." (PMID 25710488, 2015). "Given dysregulated mTOR signaling is involved in the pathogenesis of many diseases, rapamycin is not only a promising anti-aging drug but could also be effective against other diseases such as cardiovascular and metabolic disorders, infertility, and cancer." (PMID 27980219, 2017). "Abnormalities in mTOR signaling during follicular development result in various pathologies, including premature ovarian insufficiency (POI) and infertility." (PMID 39464191, 2024). "Further analysis of clinical samples revealed that, compared to patients with male-factor infertility, PCOS patients exhibited elevated c-Fos and p-mTOR/mTOR expression in granulosa cells, while ERα expression was downregulated, and ERβ expression showed no significant changes." (PMID 40937413, 2025).
Infertility (continued). "This transient and ovary-specific exposure to mTOR activators in vitro, when combined with treatment with AKT stimulators, could improve the success of infertility treatment as compared with the use of AKT stimulators alone." (PMID 25710488, 2015). "For example, suppressed autophagy has been observed in flutamide-induced neonatal cryptorchid infertile rats, and retinoic acid improved spermatogenesis by activating autophagy via inhibition of the phosphatidylinositol 3 kinase (PI3K)/Akt/mammalian target of rapamycin (mTOR) signaling pathway." (PMID 39469578, 2024). "Although the long-term health status and fertility potential of these pups remain to be evaluated, the present findings suggest that short-term exposure to mTOR signaling activators, similar to AKT signaling stimulators, could be the basis to develop future infertility therapies." (PMID 25710488, 2015).
ovarian tumor (23 papers, 2009 to 2025). "We apply TDJGL to the PI3K/AKT/mTOR pathway in ovarian tumors to build differential networks associated with platinum resistance." (PMID 27677586, 2016). "Immunohistochemical analysis was performed on the ovarian tumors after treatment with metformin or vehicle to assess effects on proliferation, apoptosis, and downstream targets of the mTOR pathway." (PMID 29340030, 2017). "In a pre-clinical study [18F]FLT uptake was decreased following effective mTOR inhibition with everolimus in a pre-clinical cisplatin-resistant ovarian tumor model." (PMID 23548101, 2013). "In addition, the intracellular level of cAMP also determines the course of other pathways including AKT, ERK, MAPK, and mTOR, that are hypo- or hyperactivated among patients with ovarian neoplasm." (PMID 36497095, 2022). "In the cholesterol synthesis pathway, SREBP2 is upregulated by salt-inducible kinase 2 (SIK2), an AMPK-related kinase, and mitochondrial elongation factor 2 (MIEF2)-activated PI3K/AKT or ROS/AKT/mTOR signaling, thus, leading to the promotion of ovarian tumor growth." (PMID 34820325, 2021). "Given that the effects of metformin to inhibit the mTOR pathway were similar between ovarian tumors from obese and lean mice, we postulate that metformin’s direct metabolic effects on inhibition of mitochondrial complex I drive the increased response in complex II-impaired tumors from obese mice." (PMID 29340030, 2017). "Thus it can be extrapolated that the upstream metabolic sensors like AMPK and SIRT1 maybe acting mainly through inhibition of mTOR, which results in deacceleration of ovarian tumor progression." (PMID 25026276, 2014). "In cell injury and apoptosis pathways, RPS7 was increased in patients with CAV and has been previously demonstrated in ovarian tumor cell lines to have pro-apoptotic functions mediated via MAPK and mammalian target of rapamycin (mTOR) signaling pathway." (PMID 40598485, 2025). "We also performed immunohistochemical staining of ovarian tumors for AKT and mTOR of mouse tumor samples." (PMID 39114948, 2024). "Both metformin, an antidiabetic drug, and everolimus, an mTOR inhibitor, suppressed TNT formation in ovarian tumor-derived epithelial and ovarian adenocarcinoma cells." (PMID 32422889, 2020). "Ovarian tumors arising in C57BL/6 TgMISIIR-TAg-DR26 mice are sensitive to standard combination platinum and taxane chemotherapy and to mTOR inhibition with Everolimus (RAD001)." (PMID 20958993, 2010). "The significant finding of this study was that ONC201 reduced the expression of DRD2, and inhibited ovarian tumor growth and reduced the ability of invasion via activation of ClpP induced oxidative stress pathways and inactivation of P13K/AKT/mTOR and MAPK pathways." (PMID 35372029, 2022). "We have previously shown that treatment with rapamycin extends mouse lifespan even when started as late as 20 months of age, suggesting that it may provide benefits related to mTOR action in growth or transformation of many different kinds of tumors, not just ovarian tumors." (PMID 27036037, 2016).
adenoma (22 papers, 2009 to 2025). A neoplasm arising from the epithelium. "ApcMin/+mice with selective myeloid cell deletion of EP4 had marked inhibition of both adenoma number and size, with associated decreases in mTOR and ERK activation." (PMID 26378024, 2015). "Adenomas of myeloid cell EP4−/−ApcMin/+ mice had decreased mTOR phosphorylation, in association with decreased expression levels of phosphorylated PI3K, PDK1, AKT and raptor." (PMID 26378024, 2015). "Biological processes more prevalent in high‐risk than low‐risk adenomas were related to proliferation, tumor microenvironment and Notch, Wnt, PI3K/AKT/mTOR and Hedgehog signaling, while metabolic processes and protein secretion were enriched in low‐risk adenomas." (PMID 31411736, 2020). "Furthermore, either genetic or pharmacologic inhibition of EP4 receptors led to inhibition of ERK and mTOR pathways in adenomas in association with decreased M2 and increased M1 phenotypic macrophages." (PMID 26378024, 2015). "Among these pathways, mTOR signaling has already been described in the literature as possibly involved in adenoma genesis." (PMID 39408812, 2024). "The results of this analysis showed that in adenoma IV, fourteen genes belonging to the mTOR pathway were present, while only five were identified in adenoma V." (PMID 39408812, 2024). "It is well known that widely invasive malignancies have a distinct profile, including activation of the PIK3CA-Akt-mTOR and Wnt/b-catenin pathways and that adenomas cluster with minimally invasive carcinomas." (PMID 38882980, 2024). "Rapamycin inhibits mammalian target of rapamycin (mTOR) protein, which is often expressed in human adenomas and CRCs." (PMID 24763434, 2014). "We have treated MMR deficient murine adenocarcinomas of the intestine and adenomas of the colon with NVP-BEZ235, a PI3K/mTOR inhibitor, as a proportion of these tumors have alterations in the PI3K/AKT/mTOR signaling pathway." (PMID 23935891, 2013). "For this reason, we assessed whether there were genes taking part in the mTOR signaling among those selectively modulated in adenomas IV, V, and VI." (PMID 39408812, 2024). "Most typical pathways were activated during the transition from normal colon epithelial cells to adenomas to carcinoma, but only the TGF-β, PI3K/AKT/mTOR, and Notch pathways were downregulated during normal to adenoma transition and activated during the transition from adenoma to carcinoma." (PMID 38098990, 2023). "Additionally, a downstream phosphorylation target and likely physiological effector of mTOR signaling, the S6 ribosomal protein, shows increased phosphorylation (phospho-S6) in roughly 40 percent of colorectal carcinomas (CRCs) and adenomas." (PMID 24763434, 2014). "The EP4 antagonist decreased adenoma phosphorylation of both ERK and mTOR, inhibited expression of arginase 1 mRNA and protein." (PMID 26378024, 2015). "Immunoblotting confirmed the decreased levels of adenoma p-ERK, p-AKT, p-mTOR and p-p70 S6K in myeloid EP4−/−ApcMin/+ mice." (PMID 26378024, 2015). "Phosphorylation of serine 2448, a key determinant of mTOR activity, was basally increased in GH3 adenoma cells." (PMID 21427787, 2011). "Furthermore, a comparison of LApc and LApcL adenoma cells in GSEA pathway analysis showed a significant increase in mTorc1 and Pi3K-Akt/mTor signaling and a decrease in Tgfβ signaling after Lef1 deletion." (PMID 34788095, 2021). "In benign lesions, three cases showed cytoplasmic positivity for mTOR (two fibroadenoma and one adenoma), while none of the benign lesions were p-mTOR positive." (PMID 23587222, 2013). "Our study reveals an interplay between Wnt/β-catenin and PI3K/mTOR, whose derangement correlates with specific microbiota signatures in FAP and CRC patients, and identifies new potential biomarkers and targets to improve CRC prevention, early adenoma detection and treatment." (PMID 38970018, 2024).
adenoma (continued). "We find that p-mTOR known to be inhibited by NVP-BEZ235, localized to the nucleus of small intestinal adenocarcinomas and to the cytoplasm of adenomas independent of treatment." (PMID 23935891, 2013).
amyotrophic lateral sclerosis (22 papers, 2010 to 2026). Amyotrophic lateral sclerosis (ALS) is a neurodegenerative disease characterized by progressive muscular paralysis reflecting degeneration of motor neurons in the primary motor cortex, corticospinal tracts, brainstem and spinal cord. "Finally, mTOR (mechanistic target of rapamycin) dysfunction has been identified as a contributing factor in human diseases such as amyotrophic lateral sclerosis (ALS), which was found to be associated with VCP mutations." (PMID 35743185, 2022). "Among the enriched pathways were ABC transporter superfamily, mTOR signaling pathway, Chagas disease, amoebiasis, amyotrophic lateral sclerosis, pyrimidine metabolism, D-arginine and D-ornithine metabolism, as well as seven other metabolic pathways." (PMID 37033246, 2023). "Rapamycin, an mTOR inhibitor and a commonly used immunosuppressive drug, has been shown to increase the survivability of Amyotrophic Lateral Sclerosis (ALS) affected motor neurons." (PMID 34518579, 2021). "For the KEGG database, the Amyotrophic lateral sclerosis pathway and MTOR signaling pathway were significantly identified with a nominal p-value Less than 0.05." (PMID 31739607, 2019). "Furthermore, amyotrophic lateral sclerosis, RNA translocation, and mTOR signaling pathway were the KEGG pathways that were most significantly enriched." (PMID 36952458, 2023). "In this section, we focus on the potential role of mTOR signaling in the pathology of Amyotrophic Lateral Sclerosis (ALS)." (PMID 32982690, 2020). "Diseases like amyotrophic lateral sclerosis (ALS), which specifically affects motoneurons, could gain from treatments which alter mTOR activity in the spinal cord." (PMID 32295297, 2020). "KEGG pathway enrichment indicated that they may play an important part in amyotrophic lateral sclerosis, TGF-beta signaling pathway, autophagy, mTOR signaling pathway, and EGFR tyrosine kinase inhibitor resistance." (PMID 35233217, 2022). "miR-193b-3p is significantly downregulated in patients with amyotrophic lateral sclerosis (ALS) and downregulation of miR-193b-3p promotes autophagy and cell survival by targeting TSC1/mTOR signaling." (PMID 36824367, 2023).
coronary artery disease (22 papers, 2017 to 2025). "Another study reveals that phagocyte autophagy is evoked by Akt inhibitors, mTOR inhibitors, and mTOR-siRNA, which indicates that activating autophagy of phagocytes will stabilize vulnerable coronary-artery disease plaques." (PMID 35498045, 2022). "In coronary heart disease as well as in hemangiomas, inhibition of the mTOR pathway blocked abnormal endothelial cell proliferation." (PMID 33390965, 2020). "Clinical trials of mTOR inhibitors in cardiovascular system is limited to drug-eluting stent after coronary heart diseases or artery stenosis." (PMID 30705773, 2019). "Taken together, our findings suggested that UB reduced the occurrence of myocardial arrhythmias after hypoxia via regulation of the Akt/mTOR pathway and NF-κB nuclear translocation, which highlights the potential of UB as a novel therapy for ischemic heart disease." (PMID 35178131, 2022). "Importantly, mTOR inhibitors could play a protective role in coronary artery disease, a common comorbidity of NAFLD." (PMID 38331795, 2024). "Interestingly, a recent clinical trial showed that the risk of occurrence of the cardiovascular event is nearly twice as great in renal transplant recipients treated with an mTOR inhibitor, and the incidence of coronary artery diseases during mTOR inhibitor therapy is higher." (PMID 30705773, 2019). "However, the role of mTOR in ischemic heart disease remains undefined." (PMID 29872406, 2018). "In coronary artery disease (CAD), mTOR signaling is integral to the regulation of endothelial function, vascular tone, and smooth muscle cell behavior." (PMID 40734978, 2025). "The present study eventually clarified that NGR1 regulated lipid metabolism in the ischemic myocardium by enhancing the binding affinity of mTOR and AKT, thus ameliorating ischemic heart diseases." (PMID 35814216, 2022). "The results of myocardial proteomics combined with network pharmacology suggested that NGR1 improves ischemic heart diseases by regulating lipid metabolism and the AKT/mTOR pathway." (PMID 35814216, 2022). "In coronary artery disease, drug eluting stents (DES) containing antiproliferative drugs such as the mTOR inhibitor Everolimus are successfully utilized to prevent restenosis by inhibiting intimal proliferation." (PMID 35845058, 2022). "Therefore, mTOR complexes and AMPK may be crucial for these HTN-T2DM and HTN hearts under coronary heart disease and preserved systolic function." (PMID 37239977, 2023).